IL6 (interleukin 6)
Diseases named in the same sentence as IL6 in open-access papers (continued):
Sharing a sentence is not in itself a finding about the gene and the disease.
diabetes (continued). "Diabetes did not induce changes neither in inflammatory cytokines (IL-1β and IL-6) nor in the profibrotic cytokine TGF-β1 at short term (1 week) (data not shown)." (PMID 26955430, 2016). "The patients suffering from PAOD with diabetes and without diabetes differed significantly in terms of the concentration of E-selectin—which was higher—and the concentrations of IL-6 and fibrinogen—which were lower—in group I compared to group II (p < 0.001)." (PMID 27834825, 2016). "In patients with diabetes, the concentration of IL-6 and fibrinogen is lower, and the concentration of E-selectin is higher than in patients without diabetes." (PMID 27834825, 2016). "Thus prolonged elevated levels of IL-6 and TNF-α can interfere with carbohydrate metabolism which can lead to glucose intolerance and diabetes mellitus." (PMID 25806806, 2015). "Hence, a cross-sectional study was conducted to determine the effect of topical melatonin application on serum TNF-α, IL-6 and CRP concentrations in patients with diabetes and periodontal disease and in a control group of healthy subjects." (PMID 26644840, 2015). "The associations of age, sex, body mass index, hypertension, hyperlipidemia, diabetes, active smoking, platelet count, WBC, IL-6, hsCRP, serum creatinine and ADMA with P-selectin expression, GPIIb/IIIa activation and MPA formation were estimated in a multivariate linear regression model." (PMID 25807315, 2015). "Glucose serum concentration at the time of blood sample, age, BMI, sex, diabetes duration, and HbA1c were not significantly correlated with IL-6 and IL-10 concentration." (PMID 25961054, 2015). "The present clinical trial study was designed to assess the effect of topical application of melatonin on serum levels of tumor necrosis factor-alpha (TNF-α), interleukin-6 (IL-6) and C-reactive protein (CRP) in patients with diabetes and periodontal disease in comparison with healthy controls." (PMID 26644840, 2015). "The administration of 1.5 g of NAC/kg/day, via gavage, for 4 weeks after induction of diabetes, increased TAS levels, in plasm, and SOD hepatic tissue activity, and inflammatory biomarkers levels were decreased in serum, for instance, TNF-α and IL-6." (PMID 26694382, 2015). "We found that the circulating proinflammatory cytokines IL-6, TNF-α and IL-Iβ, but not IFN-γ, were significantly elevated in the SENP1-deficient mice before the onset of diabetes at the age of 7 weeks." (PMID 26596471, 2015). "Regardless of definition, patients with pre-diabetes and type 2 diabetes displayed a chronic pro-inflammatory profile as characterised by elevated C3, IL-6, WBC levels and reduced adiponectin concentrations." (PMID 26266799, 2015). "In vivo administration of A-285222 completely blocked diabetes-induced NFAT-transcriptional activity in the aorta, leading to reduced expression of IL-6, OPN, MCP-1, ICAM-1, CD68 and TF, all established players in atherogenesis, as well as to reduced diabetes-induced atherosclerosis." (PMID 23755169, 2014). "Furthermore, macrophages from mice with streptozotocin- (STZ-) induced diabetes display a dysfunctional phenotype, reduced CD86 expression, and proinflammatory cytokines such as TNF-α and IL-6 production but enhanced nitric oxide (NO) secretion." (PMID 24899891, 2014). "HIF-1α levels positively correlated with CRP, IL-6, UKPDS risk score, HbA1c, FBG, and CACS, but did not correlate with diabetes duration, age, and LDL." (PMID 24564828, 2014). "In our study, HIF-1α correlated with some cardiovascular risk factors (CRP, IL-6, UKPDS, HbA1c and FBG), but were not correlated with others (diabetes duration, age and LDL)." (PMID 24564828, 2014). "Education, diabetes (n = 4) and past history of hypercholesterolemia were not related to IL-6 levels or CC integrity." (PMID 25188448, 2014).
diabetes (continued). "In the pathogenesis of diabetes mellitus, proinflammatory cytokines such as tumor necrosis factor-α (TNF-α) and interleukin-6 (IL-6) could be produced by immunocytes (like macrophages) and adipocytes." (PMID 24669227, 2014). "Specifically, inflammatory cytokines such as interleukins IL-6, IL-2, and tumor necrosis factor-α (TNF-α) are elevated in hyperglycemia, suggesting that a chronic low grade inflammatory state exists in patients with diabetes." (PMID 24961298, 2014). "In this study, which included subjects without diabetes, circulating progranulin levels had a significant positive correlation with serum hsCRP and IL-6 levels, reflecting chronic subclinical inflammation." (PMID 23409033, 2013). "Levels of IL-8 were higher in CLI patients with diabetes compared to non-diabetic patients (18.7 [13.4–25.2] pg/ml vs 14.3 [9.9–22.5] pg/ml, P = 0.048) and IL-6 levels showed a similar trend (10.5 [3.9–15.3] pg/ml vs 4.5 [1.4–11.2] pg/ml, P = 0.050)." (PMID 23383236, 2013). "In our study, we found that the levels of TNF-alpha and IL-6 in NAC-treated diabetic rats were significantly lower than that in the untreated diabetes, but still slightly higher than that in nondiabetic rats." (PMID 23853776, 2013). "We first found that diabetes induction was accompanied by an elevation in the plasma levels of reactive oxygen species (ROS), hydroperoxide, malondialdehyde (MDN), and the proinflammatory cytokines IL-1α, IL-1β, IL-6, and CXCL10." (PMID 23533683, 2013). "Diabetes significantly increased the retinal expressions of iNOS by 40%, IL-6 by 60%, and TNF-α by 35% as compared to nondiabetic rat retinas." (PMID 23671886, 2013). "In addition, several cross-sectional studies have shown an increase of CRP levels in patients with diabetes and the increase of CRP, IL-6, and TNF-alpha in subjects with IGT." (PMID 23690772, 2013). "Thus, WP supplementationduring diabetes significantly restored the levels of TNF-α, IL-1β,IL-6 and IL-10." (PMID 22708778, 2012). "Then, the aim of this study was to investigate the possible microbiological changes and the spatial distribution and the number of immunostained cells to RAGE, TNF-alpha, IL-1beta, IL-6, RANKL and MMP-2, and MMP-9, in periodontal tissue after diabetes induction." (PMID 22611374, 2012). "In the present study we demonstrated that IL-6 potently induces AMPKα2 activity in He myocytes, but not in DM myocytes derived from individuals with diabetes." (PMID 22761857, 2012). "In another study conducted in the Midwest among nonsmoking elderly individuals with comorbidities including diabetes, IL-6 increased, although not significantly, with increasing 5-day average BC, consistent with our findings for IL-6." (PMID 22336131, 2012). "In addition, supplementation with α-tocopherol resulted in decreased circulating IL-1β, IL-6, TNF-α, and CRP in individuals with diabetes." (PMID 23158971, 2012). "Surprisingly, we found that although in more severe conditions on admission to ICU, several patients with diabetes displayed a subdued inflammatory response as assessed by circulating IL-6 levels compared with non-diabetic patients." (PMID 21871056, 2011). "Plasma IL-6 and TNF-α levels were increased in the rats with diabetes." (PMID 21912612, 2011). "Both NAC and ALP significantly decreased plasma IL-6 secretion in diabetes, but the combination conferred no further benefit." (PMID 21912612, 2011). "Further, lack of TNFα prevented the up-regulation of IL-6 and IL-1β mRNA otherwise observed in wt mice in response to diabetes." (PMID 20856927, 2010). "Biological dysfunctions, found in diabetes, obesity, and the metabolic syndrome include, among others, increases in the circulating levels of metabolites, such as FFA and triglycerides, and cytokines such as TNF-α and IL-6." (PMID 20671994, 2010).
diabetes (continued). "There are several plausible diabetes and nephropathy candidate genes in the resulting region of interest, including glucokinase isoform 1 (GCK1), interleukin-6 (IL6), insulin growth factor binding protein 1 (IGFBP1) and insulin growth factor binding protein 3 (IGFBP3)." (PMID 20144192, 2010). "In vivo, Pn@Janus TPP implantation markedly enhanced alveolar bone regeneration in a diabetic rat periodontitis model, restored periodontal architecture, and reduced the expression of key pro-inflammatory cytokines (IL-6, TNF-α, iNOS, IL-1β), without inducing systemic toxicity." (PMID 41704297, 2026). "Similarly, studies have shown that there was no positive association between IL-6 single nucleotide polymorphism (SNP) rs1800795 which is associated with type 2 diabetes mellitus (T2DM) and type 1 diabetes mellitus (T1DM)." (PMID 40941639, 2025). "Beyond its local periodontal effects, SDD may also reduce systemic inflammatory mediators such as C-reactive protein (CRP), interleukin-6 (IL-6), and tumor necrosis factor-alpha (TNF-α), particularly in systemically vulnerable populations like individuals with diabetes or cardiovascular disease." (PMID 41465800, 2025). "It has been observed that type 2 diabetes mellitus patients with diabetic nephropathy have higher levels of IL-6 in the bloodstream than their counterparts without diabetic nephropathy, suggesting a significant association between IL-6 and the development and progression of diabetic nephropathy." (PMID 40003909, 2025). "Inhibited EGFR/PI3K/AKT signaling pathway, reduced the released of inflammatory factors IL-1β, IL-6, TNF-αImproved lipid and glucose metabolism, promoted adipogenesis, improved insulin sensitivity by regulating PI3K-Akt signaling pathway, and fight against diabetes and its complications." (PMID 41356003, 2025). "Furthermore, in patients with diabetes, infection with SARS-CoV-2 induces a more pronounced inflammatory response due to the excessive production of interleukins—specifically interleukin-6 (IL-6), interleukin-8 (IL-8), and tumor necrosis factor-α (TNF-α)." (PMID 40861049, 2025). "However, the correlation of the expression of IL6 in patients with diabetes mellitus type 2 in the present sample size and composition was not statistically significantly higher than in non-diabetic patients." (PMID 40523922, 2025). "CGA has been shown to modulate the production of inflammatory mediators such as TNF-α, IL-1β, IL-6, IL-8, NO, and PGE2, and regulate key signaling pathways such as NF-κB, MAPK, and Nrf2, providing protective effects against cardiovascular disease and diabetes mellitus." (PMID 40943313, 2025). "Biomarkers like interleukin-6 (IL-6), C-reactive protein (CRP), and tumor necrosis factor-alpha (TNF-α) are related to inflammation and may serve as indicators of cardiac inflammation in diabetes." (PMID 39129285, 2025). "None explored the integrated role of Interleukin-6 (IL-6) in the diabetes-brain constellation, specifically whether there is a mediating effect of IL-6 on the path between diabetes and biomarkers of cognitive decline." (PMID 40606939, 2025). "HA also has anti-inflammatory properties, as it can modulate inflammatory processes by inhibiting pro-inflammatory cytokines (IL-1, IL-6, and TNF-α), which may help control the exacerbated inflammatory response seen in periodontitis among patients with diabetes." (PMID 39595081, 2024). "Additionally, lifestyle changes such as diet and exercise can reduce IL-6 levels, presenting non-pharmacological options for managing diabetes-related inflammation." (PMID 39857603, 2024). "Moreover, the anti-inflammatory properties of sweet cherries may help manage conditions like diabetes by reducing markers of inflammation such as C-reactive protein (CRP) and interleukin-6 (IL-6)." (PMID 39519493, 2024).
diabetes (continued). "The radar chart and random forest analysis revealed that RA patients with comorbid conditions, particularly diabetes mellitus (DM), hypertension (HTN), and cardiovascular disease, exhibited significantly elevated IL-6 levels." (PMID 39469275, 2024). "Interestingly, IL-6, a difference from our previous study in the Mexican population, had no significant predictive value for the development of diabetes or cardiovascular complications." (PMID 39519313, 2024). "IL-1β, IL-6 and TFN-α are particularly relevant, contributing to cancer and the majority of inflammatory disorders, including cardiovascular disorders, rheumatoid arthritis and several other autoimmune inflammatory diseases, pulmonary inflammation, as well as type-2 diabetes mellitus." (PMID 38581641, 2024). "Hence, the present study aimed to assess the clinico-radiographic parameters as well as salivary levels of RANKL, OPG, IL-6, and TNF-α around standard implants- and SDI-supported fixed partial dentures in partially dentate type-2 diabetes mellitus (T2DM) patients treated for periodontitis." (PMID 39625348, 2024). "Therefore, the present study indicated that EPE could ameliorate the incidence of type 1 diabetes mellitus and immunoregulation accompanied by a decrease in the number of CD4+ IL-17 cells and blood cytokine levels of IL-6 through the regulation of Th17 cells." (PMID 37373070, 2023). "Moreover, they discovered an inverse correlation between 25(OH)D and mortality regardless of age, sex, diabetes, platelet count, and levels of IL-6, CRP, lactate dehydrogenase (LDH), neutrophils, and lymphocytes." (PMID 37727794, 2023). "In this cross-sectional analysis of AI participants from the SHFS, rs3740393 modified the association of reported Mg intake with IL-6 (but not CRP), after adjustment for factors known to be associated with Mg intake and inflammation, including dietary factors, prevalent diabetes, and prevalent CVD." (PMID 38128021, 2023). "Since elevated levels of IL-6 have been found in patients with co-morbid diabetes mellitus, it may not be specific to MMD." (PMID 36769472, 2023). "A multivariable analysis showed that high IL-6 levels were independently associated with an increased risk of AVF dysfunction in both patients with and without diabetes (adjusted HR = 4.81, 95% CI = 1.02–22.64, p = 0.047 and HR = 7.53, 95% CI = 1.49–38.15, p = 0.015, respectively)." (PMID 36675812, 2023). "No other significant associations were found between diabetes’ duration and evaluated cytokine parameters including IFN-γ+ PBMCs and IFN-γ MFI on CD3+ PBMCs; IL-6+ and CD3+IL-6+ PBMCs and IL-6 MFI on CD11b+ PBMCs; myeloid IL-17A+ PBMCs; CD11b+ and myeloid PBMCs." (PMID 36766809, 2023). "However, we find that although composition and overall global transcriptional pattern is similar regardless of HIV serostatus, diabetic PWH have greater contribution of inflammatory signaling pathways such as IL6, IFN-γ, and TNF compared with HIV-negative persons with diabetes." (PMID 37711619, 2023). "Finally, for those with diabetes who were not using IL-6 inhibitors, 12 mg/d was more beneficial when using IMV than NIV/cCPAP or open systems." (PMID 37085591, 2023). "Therefore, it was not surprising to notice better diabetes control after the significant declines in TNFα, IL-6, and LTB4 levels in the montelukast group compared to the placebo." (PMID 37113754, 2023). "Also, the relationship between age and IL-1β, IL-6, or TNFα production was not seen in this population compared to the healthy subjects, arguing that the presence of diabetes supersedes the impact of age." (PMID 36337734, 2022). "Actually, the impaired immune state in diabetes is characterized by an initial interruption in the activation of Th1 CD4+ T cell-mediated immunity and late hyperimmune response, which may contribute to cytokine storm dominated by IL-6." (PMID 36123740, 2022).
diabetes (continued). "In addition, the injection of nondiabetic plasma-treated SVFs not only repressed the expression of the diabetes-induced ICAM, FMO3, IL-6, IL-1β, iNOS, TNF-α, and DPP4 expression, but also suppressed the phosphorylation of JNK and NF-κB in the liver of diabetic mice." (PMID 35883204, 2022). "Previous studies have reported that increased secretion of tumor necrosis factor α (TNFα), interleukin (IL)-6, C-reactive protein (CRP), and other substances at low concentrations lead to chronic low-grade inflammatory responses accompanied by the development and progression of diabetes mellitus." (PMID 35062863, 2022). "In addition, IL-6 values below 1.5 pg/ml are related to the absence of a history of hypertension and hypercholesterolemia, diabetes, smoking, and a higher frequency of exercise." (PMID 35910449, 2022). "Diabetes increased TLR4-mediated inflammation, whereas DP inhibited the protein expression of the TLR4 pathway (TLR4, Myd88, IRAK1, and TRAF6) and reduced the mRNA expressions of IL-1β, IL-1α, IL-6, and TNF-α and the protein expressions of TNF-α, IL-1β, and COX-2." (PMID 35463063, 2022). "Thus, IL-6 and especially hs-CRP might be considered two “sensors” of LGI with a prognostic value for the development of diabetes complications." (PMID 35503137, 2022). "Whether IL6 can predict the incidence of diabetes for the HIV population is still not clear, as the findings are highly heterogenous." (PMID 36561566, 2022). "Studies have indicated that peripheral IL-6 blockade with tocilizumab may improve insulin sensitivity and glycemic control in humans with and without diabetes, where plasma IL-6 is elevated." (PMID 35470093, 2022). "In summary, this research revealed significant variations of adiponectin, nesfatin-1, IL-6, and TNF-α levels in the healthy, prediabetes, and T2DM, suggesting a significant but slow and gradual change during the progression from a healthy condition toward diabetes via prediabetes." (PMID 35311231, 2022). "The variation and correlation among adiponectin, nesfatin-1, tumor necrosis factor α (TNF-α), and interleukin 6 (IL-6), which may be involved in the development of the decline of health into prediabetes and diabetes, have not been elucidated." (PMID 35311231, 2022). "The macroalbuminuria patients exhibited higher plasma levels of ANP, TNF-α, IL-6, and ADP; higher serum creatinine (Cr) and blood urea nitrogen (BUN); and longer duration of diabetes mellitus (DM) than the patients with normoalbuminuria and microalbuminuria." (PMID 34663293, 2021). "Aging of humans is known to be accompanied by low-grade inflammation, as manifested by consistently elevated levels of inflammatory cytokines, especially interleukin-6 (IL-6) and tumor necrosis factor-α (TNF-α); these factors could promote diverse pathologic states such as diabetes and cancer." (PMID 34948277, 2021). "In this study, we first presented markedly elevated Th1 cytokine IL-2R and TNF-α levels and increased levels of Th2 cytokines, including IL-6, IL-8, and IL-10, in patients with diabetes compared with patients without diabetes among patients with COVID-19 pneumonia." (PMID 33776910, 2021). "In addition, AA showed potent anti-inflammatory action by virtue of its ability to suppress IL-6 and TNF-α production and the expression of NF-κB and prevented both alloxan- and streptozotocin-induced type 1 and type 2 diabetes mellitus in experimental animals." (PMID 34944517, 2021). "Additionally, PCB118 increased the production of inflammatory factors (IL-6, IL-18, and CCL-2) that may damage islet cells, possibly leading to the occurrence and development of diabetes." (PMID 34055976, 2021). "Moreover, vegetable intake was negatively associated with serum levels of C-reactive protein, IL-6, and TNF-α in healthy individuals without cardiovascular disease or diabetes mellitus." (PMID 33171846, 2020).